BRCA2 (BRCA2 DNA repair associated)
Diseases named in the same sentence as BRCA2 in open-access papers (continued):
Sharing a sentence is not in itself a finding about the gene and the disease.
breast cancer (continued). "Research findings suggest that U. dioica extract modulates key molecular pathways associated with obesity and breast cancer, leading to the downregulation of critical markers like Dgat1, Lpl, Fas, Mcp1, Brca1, and Brca2 in LPS induced adipocytes." (PMID 40153121, 2025). "In contrast to BRCA1 mutation carriers, BRCA2 mutated breast cancers have similar pathological features to sporadic breast cancer." (PMID 39621070, 2025). "RAD51C/RAD51D-mutated cancers and BRCA2/RAD51C hypermethylation in male breast cancer (~30% prevalence) expand PARPi candidacy]." (PMID 40864792, 2025). "Is breast-conserving treatment (BCT) comparable with mastectomy in terms of oncologic outcomes in patients with breast cancer with BRCA1 or BRCA2 pathogenic variants?" (PMID 40366658, 2025). "Second primary cancer (SPC) risks after breast cancer (BC) in BRCA1/BRCA2 pathogenic variant (PV) carriers are uncertain." (PMID 39475295, 2025). "The association of screening mammography with breast cancer (BC) was investigated in cases with a hereditary predisposition unexplained by BRCA1 or BRCA2 and unrelated controls." (PMID 40227588, 2025). "Despite advancements in genetic testing and expanded eligibility criteria, underutilisation of germline testing for pathogenic variants in BRCA1 and BRCA2 (BRCA) remains evident among breast cancer (BC) patients." (PMID 39876688, 2025). "We observed that most PVs were in known breast cancer susceptibility genes, and PVs in BRCA2 were the most frequent." (PMID 38893140, 2024). "Since the identification of the BRCA1 and BRCA2 genes, germline pathogenic and likely pathogenic variants, herein collectively termed PVs, have been associated with increased risks of breast cancer in both men and women." (PMID 38609177, 2024). "Two variants identified in the present study in BRCA2 (BRCA2 c.3482dup and BRCA2 c.8878C>T) have clear diagnostic and clinical relevance, as pathogenic variants in this gene have been proven to increase the risk of breast cancer." (PMID 39126233, 2024). "Most such families are explained by a mutation in either of the well-known breast-ovarian cancer genes BRCA1 and BRCA2, which account for approximately 10–15% of cases with familial risk of breast cancer." (PMID 38397208, 2024). "BRCA1 and BRCA2 are well-characterized breast cancer susceptibility genes and it is well established that mutations in these genes impair the homologous recombination–mediated DNA repair pathway, which is required to maintain genomic integrity." (PMID 38059556, 2024). "CSTF1, pivotal in DNA damage repair, is linked to increased breast cancer risk in BRCA2 mutation carriers due to CSTF1 mutations." (PMID 39185313, 2024). "Young women who develop breast cancer before the age of 40 often harbor a pathogenic germline variant in the BRCA1 or BRCA2 gene." (PMID 38398129, 2024). "Studies of populations in the USA or Europe have shown that BRCA1 and BRCA2 mutations have a 24–35% and 19–29% risk of developing contralateral breast cancer within 10 years of their first breast cancer." (PMID 38254240, 2024). "Half of paraffin-embedded tissue sections from human breast cancers exhibit APBs and telomere length heterogeneity, suggesting that BRCA2 mutations can predispose individuals to ALT-type tumorigenesis." (PMID 38587189, 2024). "Many pathogenic gene mutations common to breast cancer, such as Pten, Brca2, Atm, Cdh1, Chek2, Nf1, Arid1a, Pik3ca, and Esr1, revealed no alterations between NT2.5 and NT2.5-LM." (PMID 38717519, 2024). "Drug efflux, BRCA1/BRCA2 reverse mutations, epigenetic modification and restoration of PARylation79 were found in breast cancer." (PMID 37588193, 2024). "Germline mutations in BRCA1 and BRCA2 (gBRCA1/2) are required for a PARP inhibitor therapy in patients with HER2-negative (HER2−) advanced breast cancer (aBC)." (PMID 39003306, 2024).
breast cancer (continued). "Genetic mutations, such as BRCA1 (Breast Cancer Gene 1) and BRCA2 (Breast Cancer Gene 2): Genetic mutations, particularly in BRCA1 and BRCA2 genes, significantly increase hereditary breast cancer risk." (PMID 38699635, 2024). "MLH1 loss suppresses growth of BRCA2-deficient tumors, and its low expression correlates with better prognosis in breast cancer patients." (PMID 38271119, 2024). "BRCA1 and BRCA2’s PVs were associated with breast cancer, ovarian/fallopian cancer, pancreas cancer, prostate cancer, and melanoma, while breast, prostate, thyroid, kidney, colon and stomach cancers were related to PVs in CHEK2." (PMID 38929805, 2024). "For a BRCA2 PV carrier with an affected mother at age 40, the breast cancer risk by age 80 is predicted to be 72.5%, compared to the 87% BC risk obtained in the previous version." (PMID 39072245, 2024). "Heredity accounts for only 5–10% of breast cancer cases, with germline mutations in BRCA1 or BRCA2 accounting for 30% of inheritable breast cancer cases." (PMID 38672665, 2024). "As an example, mutations in the BRCA1 and BRCA2 genes are well known to be associated with increased risk of breast cancer." (PMID 39729424, 2024). "Female BRCA2 mutation carriers’ lifetime risks are reported to be 69% for breast cancer and 17% for ovarian cancer." (PMID 39590130, 2024). "Even though rarer than BRCA1 and BRCA2, a short list of other highly penetrant genes are known to elevate breast cancer risk." (PMID 39402389, 2024). "Germline pathogenic variants in BRCA1 and BRCA2 genes (gBRCAm) are the most common hereditary breast cancer predisposition." (PMID 39319938, 2024). "More than half of the respondents (55%) were aware that mutations in the BRCA1 or BRCA2 genes predispose women to cervical cancer and breast cancer." (PMID 39728052, 2024). "BRCA2-mutated carriers have a high lifetime risk of breast cancer (BC), an early age of onset, and an increased risk of other cancers (including ovarian, pancreatic, and prostate cancer)." (PMID 38184581, 2024). "The epidemiology of breast cancers arising in the context of a BRCA1 or BRCA2 mutation is different than that of sporadic cancers." (PMID 39060255, 2024). "The most prevalent germline mutations linked to breast cancer occur in the BRCA1 and BRCA2 genes (breast cancer gene 1 and gene 2), vital for DNA repair, carrying an average cumulative lifetime risk of approximately 70%." (PMID 39065193, 2024). "In this case, we describe the management of a male breast cancer patient with both BRCA2 and BRIP1 deleterious gene mutations." (PMID 38912178, 2024). "In a recent Swedish publication, the percentage of carriers of a pathogenic variant in BRCA1 or BRCA2 among women diagnosed with breast cancer at 40 years or younger was 10.0% (105/1055 patients)." (PMID 38491334, 2024). "Recent research demonstrates that individuals harboring BRCA2 mutations have a higher risk of developing male breast cancer, prostate cancer, and pancreatic cancer than those with BRCA1 mutations." (PMID 38255960, 2024). "Twenty-six different BRCA2 mutations were identified in breast cancer patients, comprising twenty-five pathogenic variants and a likely pathogenic variant." (PMID 38167124, 2024). "In order to monitor the elevated risk of breast cancer in women with pathogenic BRCA1 or BRCA2 gene mutations, MRI is used." (PMID 39449897, 2024). "There are several polymorphisms of BRCA1 and BRCA2 associated with increased risk of sex-specific cancers such as breast cancer, ovarian cancer, and endometrial cancer in women and prostate cancer in men." (PMID 38952711, 2024). "Carriers of BRCA1 and BRCA2 mutations face a cumulative breast cancer risk of 72% and 69% respectively by the age of 80." (PMID 38167124, 2024).
breast cancer (continued). "Two genes commonly associated with breast cancer are BRCA1, BRCA2 (breast cancer-associated genes), and the HER2 gene (human epidermal growth receptor 2)." (PMID 39877793, 2024). "For the example of female breast cancer, individuals in the top 0.3% of the breast cancer Enhanced PRS distribution have an equivalent average lifetime risk to deleterious mutation carriers for BRCA1 or BRCA2 genes in UK Biobank (35% to age 70)." (PMID 39292644, 2024). "The present study aimed to detect the frequencies of inherited breast cancer caused by BRCA1 and BRCA2 genes among Kurdish breast cancer patients, including all the exome of these two genes, using next-generation sequencing (NGS)." (PMID 38863777, 2024). "Kuchenbaecker and the BRCA1 and BRCA2 Cohort Consortium9 reported in their study that the cumulative risk of developing breast cancer by age 80 years is 72% for BRCA1 mutation carriers and 69% for BRCA2 mutation carriers." (PMID 38717180, 2024). "**Breast cancer-specific risk factors: BRCA1/BRCA2 mutation status, early menarche, late menopause, high-density breast, first pregnancy after age 30, not breastfeeding, never having a full-term pregnancy." (PMID 38496074, 2024). "In contrast, BRCA1 P/LP variant detection increased from 74% to 91%, and BRCA2 detection increased from 45% to 87% for current practice and testing of all breast cancers, respectively." (PMID 39766065, 2024). "The BRCA1 and BRCA2 genes are key breast cancer risk factors, and they are involved in DNA damage repair, cell cycle control, apoptosis, and gene transcriptional regulation." (PMID 38711004, 2024). "PALB2 (partner and localizer of BRCA2) is considered a high-risk gene in breast cancer, and it encodes for a protein with tumor suppressor activity." (PMID 38784039, 2024). "The same numbers of BRCA1 and BRCA2 mutations and the same ratios of luminal and triple negative (TN) breast cancer cases were observed." (PMID 39544591, 2024). "For example, variant rs11571833 (chr13:32398489; c.9976A>T) is a rare truncating mutation in BRCA2, associated with low breast cancer risk." (PMID 39272813, 2024). "By means of this approach, we successfully mapped SREs in the breast cancer (BC) susceptibility genes BRCA2 (MIM#600185), including exon 17 with a GC-5′ss, CHEK2 (MIM#604373), and RAD51D (MIM#602954)." (PMID 39518003, 2024). "Women harboring BRCA1 or BRCA2 (BRCA) germline pathogenic sequence variants (PSVs) are at a substantially increased lifetime risk for developing breast cancer (BC) estimated at 72% and 69%, respectively, at times diagnosed at an early age—< 40 years." (PMID 38379091, 2024). "Tamoxifen, which has been shown to reduce breast cancer incidence by 62% in unaffected BRCA2 mutation carriers in a small study comparing its effectiveness with a placebo, is one option." (PMID 39590130, 2024). "This cohort study examines the association between magnetic resonance imaging (MRI) surveillance and the risk of breast cancer mortality in women with BRCA1 or BRCA2 sequence variations." (PMID 38421676, 2024). "Data are scarce on the role of pathogenic germline variants in BRCA1 and BRCA2 (gBRCAm) in subtype-specific survival in young women who develop breast cancer under the age of 40." (PMID 38398129, 2024). "MLH1 tends to have an insignificant impact on the survival of patients with other cancers (3 G–J and L–O), supporting a tissue-specific role of MLH1 in BRCA2-associated breast cancer." (PMID 38271119, 2024).
breast cancer (continued). "For BRCA2 mutation carriers, a risk-reducing mastectomy was associated with an 86% reduction in the risk of developing subsequent breast cancer during the same follow-up period." (PMID 38791944, 2024). "While the biological subtype in the patients with pathogenic variants of BRCA2 resembles distribution of sporadic breast cancers to a great extent, most breast cancers in pathogenic BRCA1 variant carriers have TNBC subtype." (PMID 39319938, 2024). "BRCA1 and BRCA2 mutations account for about 40–50% of hereditary breast cancers and about 5–10% of all breast cancers." (PMID 38791944, 2024). "Women possessing a pathogenic BRCA1 or BRCA2 variant were found to be at an elevated susceptibility to breast cancer, wherein this risk appears to be more pronounced amongst individuals with a first-degree familial background." (PMID 38391399, 2024). "Breast cancer gene 1 (BRCA1) and BRCA2 are well-known mutations responsible for approximately half of the hereditary breast cancer and belong to the class of high-penetrance breast cancer susceptible genes." (PMID 38464382, 2024). "A study combining data from 22 investigations found that by age 70, 65% of women with BRCA1 and 45% with BRCA2 variants develop breast cancer." (PMID 39598249, 2024). "Incidentally, this variant is located in the BRCA2 ovarian cancer cluster regions (OCCRs), where a small but statistically significant difference in the mean age at breast cancer diagnosis was found." (PMID 39126233, 2024). "Germline pathogenic variants in BRCA1 and BRCA2 account for approximately 5% of all breast cancers and up to 30% of hereditary breast cancer." (PMID 38869771, 2024). "Conversely, for those with a BRCA2 mutation, the risk of breast cancer ranges from 40–45%, while the risk of ovarian cancer is between 15–30%." (PMID 39594243, 2024). "BRCA1 and BRCA2 are genes strongly linked to breast cancer, primarily due to their roles in DNA damage repair." (PMID 39598249, 2024). "PDXs were derived from brain metastasis of triple-negative breast cancer (TNBC), estrogen receptor–positive/progesterone receptor–positive (ER+/PR+) primary breast cancer from a BRCA2-mutation carrier, and pleural effusion from an ER+/PR− breast cancer." (PMID 38651826, 2024). "In our recent work, we have found that PARG loss is the most frequently detected PARPi-resistance mechanism in mammary tumors from BRCA2-deficient triple-negative breast cancer (TNBC) mouse models." (PMID 38360994, 2024). "The identification of mutations in the BRCA1 and BRCA2 genes, pivotal in HR repair of DSBs, was associated with a breast cancer risk as high as 70% and emphasized the importance of intact DDR in mitigating cancer risk." (PMID 40191738, 2024). "Mutations in high-risk genes, such as breast cancer association 1 or 2 genes (BRCA1 or BRCA2), have long been linked with breast cancer heritability." (PMID 39596875, 2024). "To summarize, mutations in BRCA1 and BRCA2 significantly increase breast cancer risk, and PARP inhibitors like olaparib and talazoparib have been effective in targeting these mutations." (PMID 38256428, 2024). "The RAD52 p.Ser346Ter allele has been associated with a reduced risk of developing breast cancer in BRCA2 carriers, and to a lesser extent in BRCA1 carriers." (PMID 38255007, 2024). "In another study that involved 616 younger patients diagnosed with breast cancer at age 40 or younger; 75 (12.2%) patients had P/LP variants; two of the BRCA2 mutations were novel." (PMID 39507757, 2024). "The most prevalent pathogenic variant of the BRCA1 among breast cancer patients was c.2635G > T, while the most common pathogenic variant of the BRCA2 was c.5164_5165del." (PMID 38167124, 2024). "Poly(ADP-ribose) polymerase (PARP) plays an essential role in single-strand DNA repair, and PARP inhibitors have shown anticancer activity against HER2-negative breast cancer cells associated with BRCA1/BRCA2 mutations." (PMID 39690423, 2024).
breast cancer (continued). "BRCA2-mutated breast cancers are often found in hormone receptor-positive, which exhibit a lower histological grade and mitotic index." (PMID 39484212, 2024). "What is the breast cancer mortality risk of women with a BRCA1 or BRCA2 sequence variation after entering a magnetic resonance imaging (MRI) surveillance program?" (PMID 38421676, 2024). "In this context, genetically engineered mouse models (GEMMs) of BRCA1- and BRCA2-associated breast cancer have proven invaluable advantages." (PMID 38789420, 2024). "We observed a similar effect of MLH1 loss on fork instability in BRCA2-proficient Mlh1KO/KO mouse embryonic fibroblasts (MEFs) as well as BRCA2-proficient KB2P1.21R2 mouse mammary tumor cells." (PMID 38271119, 2024). "Initial studies have shown that individuals with BRCA1 or BRCA2 mutations were 84% more susceptible to breast cancer and 40% more susceptible to ovarian cancer throughout their lifetime 30-32." (PMID 38706918, 2024). "In contrast, bilateral salpingo-oophorectomy has been shown to reduce the risk of ovarian cancer by 80% and the risk of breast cancer by 50% in BRCA2 mutation carriers, and it has been proven to have a survival benefit." (PMID 39590130, 2024). "The use of PARP inhibitors, such as olaparib and talazoparib, has shown effectiveness in treating breast cancer with BRCA1 or BRCA2 mutations." (PMID 38256428, 2024). "For example, a breast cancer-associated BRCA2 variant reduces interactions with DDX5 and results in a decrease of DDX5 at R-loops." (PMID 38858601, 2024). "A semi-annual surveillance scheme from age 25 to 30 years is offered to BRCA1/BRCA2 pathogenic sequence variants (PSVs) carriers for early detection of breast cancer (BC)." (PMID 38379091, 2024). "Moving beyond BRCA1 and BRCA2, rare germline pathogenic variants (PVs) in other genes that have a role in the DNA repair pathway of homologous recombination also confer risks for breast cancer." (PMID 39001430, 2024). "This is supported by the fact that overexpression of DNA2 blocks the MRE11-mediated fork degradation in Brca2-deficient mouse mammary tumor cells." (PMID 38271119, 2024). "While breast cancer 2 (BRCA2) loss of heterozygosity (LOH) promotes cancer initiation, it can also induce death in nontransformed cells." (PMID 38557488, 2024). "Magnetic resonance imaging (MRI) surveillance is offered to women with a pathogenic variant in the BRCA1 or BRCA2 gene who face a high lifetime risk of breast cancer." (PMID 38421676, 2024). "Numerous breast cancer patients carrying germline mutations in the breast cancer 1 (BRCA1) or BRCA2 genes display specific subtypes of the disease." (PMID 39690423, 2024). "Prospective studies have shown that only 5–12% of all women younger than 40 years with a first breast cancer diagnosis were carriers of the BRCA1 or BRCA2 mutation." (PMID 38254240, 2024). "In summary, we identified DNA double-strand break repair pathway BRCA2 variant in patients with both familial breast cancer and prostate cancer with bone metastases." (PMID 39364320, 2024). "BRCA1 and BRCA2 are tumor suppressor genes that have been linked to inherited susceptibility of breast cancer." (PMID 39237557, 2024). "Many genes, such as the tumor suppressor genes BRCA1 and BRCA2, have been found to be closely associated with the occurrence and development of breast cancer." (PMID 38244591, 2024). "Both men were studied for the same familial variant (BRCA2: c.6275_6276delTT) identified in a female index case with breast cancer." (PMID 38566764, 2024). "This review article sheds light on the differences in tumour microenvironment between sporadic breast cancers and BRCA1 and, to a lesser extent, BRCA2 pathogenic variant (PV)-associated breast cancers, which are usually hereditary." (PMID 39682099, 2024). "BReast CAncer gene 2 (BRCA2) plays an essential role in DNA repair through homologous recombination, and heterozygous germline defects in BRCA2 increase the risk of breast cancer." (PMID 38377393, 2024).